INS (insulin)
Diseases named in the same sentence as INS in open-access papers (continued):
Sharing a sentence is not in itself a finding about the gene and the disease.
diabetes (continued). "Given that insulin is the sole hormone effectively reducing blood glucose levels, and in STZ-induced diabetes, insulin deficiency is not accompanied by insulin resistance, the anti-hyperglycemic effect of baicalin is due to an elevation in blood insulin levels." (PMID 38203600, 2023). "Finally, this study used electronic prescription records for insulin/insulin analogues as a proxy for diabetes rather than depending on diagnoses recorded in electronic hospital/medical records." (PMID 36869270, 2023). "The highest C statistic was from the external validation of the diabetic model; this model included age, sex, race, ethnicity, eGFR, history of cardiovascular disease, ever smoker, hypertension, body mass index, albuminuria, diabetes medications (insulin vs only oral medications vs none), and HbA1c." (PMID 37079751, 2023). "A subgroup analysis was conducted to investigate heterogeneity using known factors that might influence circulating insulin, including participants (with vs. without diabetes) and intervention type (supplement/extract vs. food)." (PMID 37221605, 2023). "This inclusion was regardless of the specific diabetes status; in particular, it did not consider whether the diabetic patient receives oral glucose-lowering drugs only or is on insulin treatment." (PMID 35976428, 2023). "After adjustment for insulin therapy, the difference in testosterone levels (including total testosterone, bioavailable testosterone, and sex hormone-binding globulin) disappeared in all patients with diabetes, regardless of gender." (PMID 37900148, 2023). "Diabetes technology continues to advance, with more individuals with type 1 diabetes (T1D) adopting insulin pumps, continuous glucose monitoring (CGM), and automated insulin delivery (AID) systems that integrate real-time glucose data with an algorithm to assist with insulin dosing decisions." (PMID 37522857, 2023). "There is no other official indication for insulin than the treatment of diabetes mellitus." (PMID 37206113, 2023). "A UK Biobank cohort conducted on 112,493 people without any cardiometabolic disease and insulin-independent diabetes in the age range of 40–69 years clearly indicated that greater MD compliance was related to decreased probability of diabetes within the UK Biobank." (PMID 38201865, 2023). "However, post-TPIAT glycemic control and insulin requirements can be variable, and it can be difficult for clinicians and families to conceptualize exchanging the symptoms of ARP/CP for the burden of diabetes management." (PMID 40303247, 2023). "The results of our study show that increased carbohydrate intake did not significantly worsen diabetes compensation in elderly patients with type 2 diabetes, even though the administration of oral antidiabetic drugs and/or insulin did not change during the study." (PMID 36678311, 2023). "Conversely, however, no more than 1% of patients with diabetes mellitus may demonstrate overt primary hyperparathyroidism, which suggests that states of insulin resistance may occur as a secondary manifestation of hyperparathyroidism." (PMID 37350980, 2023). "Rates of intracranial hemorrhage were 0.18%/year in non-diabetic patients, 0.18%/year in diabetic patients without insulin therapy (HR 0.97, 95% CI 0.43–2.17, p = 0.93 vs no diabetes) and 0.56%/year in diabetic patients on insulin (HR 3.04, 95% CI 1.28–7.22, p = 0.012 vs no diabetes)." (PMID 35976428, 2023). "However, when first-phase insulin secretion was analyzed by taking into account either the degree of IR or basal insulin secretion, they found that women with PCOS who have a family history of diabetes were significantly more likely to demonstrate impairments in beta cell function." (PMID 36834549, 2023). "BMI, baseline insulin dose, and diabetes duration did not predict response." (PMID 37589043, 2023). "The prevalence of diabetes mellitus was 37.1%, but none of the patients required insulin treatment." (PMID 36050624, 2023).
diabetes (continued). "•Compared to those without diabetes, some data suggests that type 2 diabetes mellitus may modestly increase resting metabolic rate, but decrease insulin-induced thermogenesis." (PMID 37990681, 2023). "Insulin production is either absent or decreased in diabetes patients, leading to hyperglycemia." (PMID 37240430, 2023). "This study identified an unacceptably high number of unknown hypoglycaemic episodes among older home-dwelling people with diabetes receiving home care, even among those not using insulin or sulfonylurea." (PMID 37817166, 2023). "The study found that new dentures, whether traditional or implant-supported, did not significantly alter the dietary intake of patients with good metabolic control of diabetes, regardless of insulin use." (PMID 37790059, 2023). "The mFI-5 score is calculated based on the presence of 5 comorbidities (congestive heart failure, diabetes mellitus regardless of insulin dependency, chronic obstructive pulmonary disease or pneumonia, partially dependent functional health, and hypertension requiring medication)." (PMID 36836553, 2023). "Cdk4-R24C rescue of Irs2–/– diabetes was not due to improved insulin sensitivity." (PMID 37712417, 2023). "The term diabetes, which was first used by the Greek doctor Aretus in the 2nd century, was defined by the WHO in 1999 as a metabolic disorder resulting in disruptions in carbohydrate, fat, and protein metabolism due to insulin secretion or the effects of insulin." (PMID 37048331, 2023). "During our study, a male patient from Palestine was referred for genetic testing after developing isolated diabetes aged 6 months (insulin treated) and presenting with severe diabetic ketoacidosis aged 5 years resulting from lack of access to insulin which was subsequently fatal (patient III.1)." (PMID 36600150, 2023). "Previous studies comparing glucose-related outcomes between insulin- and noninsulin-treated patients with diabetes mellitus and CKD found a mean HbA1c of 7.5% (58 mmol/mol) among insulin-treated patients compared to 6.7% (50 mmol/mol) among those who were noninsulin-treated." (PMID 37152098, 2023). "The hypothesis of this study was that BPA would affect the insulin-secreting β-cells by inducing an ER stress response, which could not be ameliorated by an adaptive UPR, leading to a dysfunctional cell with severe consequences in diabetes." (PMID 36768343, 2023). "Hence, it can alter insulin levels in people who have diabetes without a statistically considerable difference from healthy subjects." (PMID 36577716, 2023). "We performed, in older individuals (>65 years) without known diabetes, a cross-sectional, longitudinal evaluation of the association of the shape of the glucose response curve with GLP-1 and GIP secretion, and GE as well as insulin secretion and sensitivity." (PMID 37764673, 2023). "The discrepancy in insulin content between the two models may be due to that the knock-down specifically focus on the effect of RHOT1, whereas in the GK rat, Rhot1 is probably one of several factors, which together contribute to diabetes." (PMID 38086799, 2023). "Though drug use in patients with diabetes mellitus was not investigated in detail, patients who used subcutaneous insulin or were currently using it may have preferred JAKis because they were orally administered." (PMID 36626396, 2023). "The use of an isCGM as the first choice at diabetes onset may be preferred, as it provides a less expensive device with automatic transmission of data, does not need calibrations, and is approved for insulin dosing without SMBG." (PMID 37676398, 2023). "Patients with long-standing diabetes, dependent on insulin administration, and with cardiovascular complications were chosen and compared with 10 age-matched individuals not diagnosed with diabetes as a control group." (PMID 36364861, 2022).
diabetes (continued). "In contrast to type 1 diabetes, MODY patients rarely have a severe presentation with ketoacidosis and weight loss, do not have islet autoantibodies, have significant endogenous insulin production outside of the honeymoon period and are very likely to have a parent affected with diabetes." (PMID 35445424, 2022). "As the transit of insulin from the endoplasmic reticulum (ER) to the plasma membrane requires glycines retained in the insulin receptor, a lack of insulin receptors induces hyperglycaemia and diabetes." (PMID 36552644, 2022). "In conclusion, in this real‐world, prospective study with a long follow‐up duration at 10 diabetes centers in China, we investigated the habits of doctors on the choice of insulin initiation patterns when non‐insulin medication failed to meet glycemic control targets." (PMID 35023626, 2022). "Also, we did not record type 1 diabetes, duration of diabetes, the standard of care (antidiabetic agents or insulin) given to patients, and quality of care." (PMID 35769727, 2022). "Diabetes is a chronic disease highly influenced by diet where individuals either do not produce enough insulin to regulate blood glucose level or they are not able to use the insulin they produce to effectively move blood glucose into body cells." (PMID 36014790, 2022). "Diabetes is a hereditary illness that develops while the pancreas does not contain enough insulin." (PMID 36238678, 2022). "Diabetes results from high blood sugar due to a shortage or lack of insulin production." (PMID 35052268, 2022). "Curiously, insulin therapy did not rescue the diabetes-induced repression of Cyp2r1 in the liver." (PMID 35524739, 2022). "As only the level of insulin increased significantly and diabetes did not develop at this time, the change in islets might suggest that compensatory hyperplasia occurred." (PMID 35683981, 2022). "Although no studies were conducted specifically on the effect of glutamine-supplemented PN in patients with diabetes, critically ill patients receiving glutamine-supplemented PN have less hyperglycemia and need insulin less frequently than patients receiving PN without glutamine." (PMID 36992742, 2022). "Compared to type 1 autoimmune diabetes (T1D), ketoacidosis at the onset of diabetes is rare in Wolfram Syndrome even if it is not excluded and the patients have a longer duration of the remission period, lower insulin requirements and a good metabolic control as demonstrated by the levels of HbA1c." (PMID 35270448, 2022). "Anyhow, subjects with diabetes using insulin lispro may undergo hypoglycemic conditions if they do not take a meal for 15 min after taking medicine." (PMID 35723344, 2022). "Diabetes mellitus is a worldwide-spread chronic metabolic disease that occurs when the pancreas fails to produce enough insulin levels or when the body fails to effectively use the secreted pancreatic insulin, eventually resulting in hyperglycemia." (PMID 36140073, 2022). "Keeping in mind the possibility of erroneous recording of diagnostic codes, some patients with type 2 diabetes (or some other type of diabetes) who received no other treatment than insulin may have been falsely identified as patients with type 1 diabetes." (PMID 36068573, 2022). "Additionally, the present study did not contain a group of T2DM patients without SCAD as a negative control, and there were no data for the plasma insulin and C-peptide levels as well as the mean duration of diabetes to evaluate the severity of T2DM." (PMID 36714594, 2022). "Thus, calystegines would improve the functions of ASCs cells through their ability to restore insulin signalling, confirming their utility as antidiabetic and antihyperglycaemic agents, which has even been proven in an in vivo model of STZ-induced diabetes in albino mice." (PMID 35327652, 2022).
diabetes (continued). "The vaccination has demonstrated some benefits in the management of diabetes, starting with bacteria, insulin, β-cells, and GAD65, though diabetes patients could not be fully treated for a variety of reasons." (PMID 36405706, 2022). "Although CD4+ T cells are essential for the triggering and progression of diabetes, T1D development requires important contributions from cytotoxic CD8+ T cells that destroy β cells of the islets of Langerhans, leading to insufficiency of circulating insulin in NOD mice." (PMID 35502705, 2022). "However, the expense related to diabetes treatment, not the method of insulin administration, was the strongest predictor of T1DM patients’ QoL." (PMID 35915454, 2022). "However, the role of glucose in society cannot be explained without mentioning the disease diabetes mellitus, a disorder derived from high glucose concentration in blood due to different reasons: abnormal insulin secretion, resistance to insulin, or both." (PMID 36015999, 2022). "When we analyzed the diabetes patients with CRD, it was found that the use of fast- and long-acting insulin increased gradually, whereas premixed and shorting- and intermediate-acting insulin use decreased significantly (p <.0001 for 2016 vs. 2017, 2017 vs. 2018)." (PMID 36093107, 2022). "Diabetes mellitus is a chronic, non-communicable, metabolic disease characterized by hyperglycemia and is attributed to a combination of defective insulin secretion by β-cells of the pancreas and the inability of insulin-sensitive tissues to respond to the secreted insulin." (PMID 36363562, 2022). "Children and adolescents living with Type 1 Diabetes (T1DM) in India face multitude of challenges including lack of free supply of insulin, syringes, glucose measuring devices and strips, lack of structured diabetes education and counselling, and inadequately trained health care professionals." (PMID 37384263, 2022). "In postmenopausal women without diabetes, short-term treatment with raloxifene did not alter fasting blood glucose or insulin levels; however, long-term administration of this medication may contribute to a decreased insulin sensitivity." (PMID 36140292, 2022). "Thus, our research suggests that allicin may alleviate diabetes by inhibiting the formation of AGEs and reducing RAGE levels to relieve oxidative stress and promote insulin secretion." (PMID 36557926, 2022). "this study shows that the increased duration of diabetes, insulin use, lack of regular physical exercise, hypertension, hypolipidemia treatment, high serum creatinine, and LDL-C were significant risk factors for chronic complications of T2DM in Moroccan patients." (PMID 35655685, 2022). "In addition, prices for noninsulin diabetes medications increased at a faster rate than prices for insulin products (76% vs 50%) during that period." (PMID 35029667, 2022). "Moreover, people with diabetes who smoke are more likely to have trouble with insulin dosing and disease management compared to non-smokers." (PMID 35565096, 2022). "“They believe in some supplement that could help with the diabetes like some cooling herbal tea rather than taking the medications from the hospital or if they require insulin injection daily." (PMID 35282452, 2022). "Nonetheless, beta cells from subjects without diabetes were positive for both amylin and insulin." (PMID 35456307, 2022). "Recently, several publications on prediabetes and overt T2DM characterized a scheme of metabolic heterogeneity in large non-interventional cohorts by defining diabetes subphenotypes, defined by glycemic state, insulin sensitivity and insulin secretion, liver fat and BMI." (PMID 36432409, 2022). "As stated in reported literature, various insulin injectables and distinct anti-diabetic compounds in the form of oral contraceptive and injections are available for the treatment of diabetes but does not provide complete cure because of side effects and cost compromise remedy." (PMID 36115959, 2022).
diabetes (continued). "Oral diabetes agents, such as insulin secretagogues, metformin, and thiazolidinediones are generally not recommended in CFRD, though some early research suggests the insulin secretagogue repaglinide may have some utility in the treatment of early CFRD." (PMID 35268004, 2022). "The hormonal response to exercise could be affected in diabetes: postprandial suppression of glucagon, increase of GLP-1, and no change in insulin levels was observed in diabetes patients one day after performing two long bouts of exercise." (PMID 35612843, 2022). "I have no breasts, I have diabetes, I take insulin four times a day." (PMID 35897424, 2022). "In a time of increasing diffusion of personalized medicine, longitudinal studies specifically designed to assess the effectiveness of treatments promoting the preservation and recovery of β-cell function and that of insulin sensitivity in non-obese individuals with diabetes should be encouraged." (PMID 36614099, 2022). "However, our sensitivity analysis, excluding people with diabetes who were taking oral glucose-lowering drugs, with or without insulin, or had missing information regarding glucose-lowering therapies, showed that the outcomes were essentially unchanged." (PMID 36079764, 2022). "Therefore, despite the large number of studies suggesting an association between cancer and some antidiabetic drugs, the consensus states that the data are not significant enough to change therapeutic approach in diabetes, especially with regard to insulin." (PMID 35893093, 2022). "Upon proper comparison, it may be discovered that glucometers should not be used to diagnose diabetes but may instead be suitable for patient monitoring and insulin management." (PMID 34976197, 2022). "Importantly, insulin can modulate the clearance of extracellular Aβ oligomers through regulating the insulin-degrading enzyme (IDE), which represents a key molecular link between AD and type 2 diabetes mellitus (T2DM)." (PMID 36010613, 2022). "The most important function of AMPK, which makes it the molecule of interest in diabetes, is its activation of glucose uptake by GLUT 4 transporters through the process involving TBC1D1, so that an insulin sensitive cell may be able to uptake and utilize the glucose." (PMID 35956652, 2022). "The existing strategy to alleviate diabetes mainly involves oral anti-hyperglycemic agents (biguanides, sulfonylureas, glucagon-like peptide-1 (GLP-1) receptor agonists, insulin sensitizers, α-glucosidase inhibitors, and thiazolidinedione), which may be accompanied by many side effects." (PMID 36337615, 2022). "This serial cross-sectional study of NHANES data from 1988 to 2020 demonstrated that despite advancements in insulin formulations and diabetes management strategies, glycemic control and severe hyperglycemia among adults using insulin did not improve in the general US adult population with diabetes." (PMID 36538330, 2022). "However, METS-IR less than the threshold was only negatively associated with CVDs-related death risk in subgroups with ≤ 65 years, male, White, non-White, already diagnosed diabetes, or uesd oral drugs, insulin, insulin sensitizing drugs." (PMID 35647046, 2022). "Although the impact of glucagon and insulin on the expression of genes was well understood, their metabolic outcome was not thoroughly understood until it became clear that diabetes could be reversed by inhibiting Foxo1." (PMID 36381916, 2022). "We speculated that increased FA 18:2 and SM 40:7 levels may impair beta-cell function rather than insulin sensitivity and thus contribute to (pre)diabetes, but further investigation needs to be conducted in the future." (PMID 36060983, 2022). "However, the gene networks contributing to dysregulated insulin secretion and the pathogenesis of diabetes is not fully understood." (PMID 36145242, 2022). "However, resting β cells by insulin injections was immunogenic and failed to prevent T1D in the Diabetes Prevention Program Trial." (PMID 35937815, 2022).